INS (insulin)
Diseases named in the same sentence as INS in open-access papers (continued):
Sharing a sentence is not in itself a finding about the gene and the disease.
diabetes (continued). "Those include the UK Prospective Diabetes Study (UKPDS), the Diabetes Mellitus Insulin-Glucose Infusion in Acute Myocardial Infarction (DIGAMI) trial, the DIGAMI-2 study, and, more recently, the Outcome Reduction with an Initial Glargine Intervention (ORIGIN) trial." (PMID 23209929, 2012). "Although people with CKD-alb and CKD-eGFR <60 were more likely to be on insulin and RAAS agents than people with non-CKD, only the 80% on RAAS agents approached Canadian Diabetes Association CPG guidelines recommending their use in those with CKD." (PMID 22776036, 2012). "The REACTION project aims to support long-term management of diabetes based on the identified user requirements through modern advanced ICT solutions enabling wearable, continuous blood glucose monitoring, and automated closed-loop delivery of insulin." (PMID 23612026, 2012). "Glucagon-like peptide-1 (GLP-1) is an incretin hormone responsible for amplification of insulin secretion when nutrients are given orally as opposed to intravenously and it retains its insulinotropic activity in patients with type 2 diabetes mellitus (T2D)." (PMID 22973260, 2012). "We assessed endogenous insulin secretion in 102 participants with insulin treated diabetes (58 Type 1) following a standardised mixed meal without exogenous insulin." (PMID 22681724, 2012). "Current diabetes therapies do not address the key driver of this condition, β-cell dysfunction, and do not alter the progressive nature of insulin secretory deficit." (PMID 23213296, 2012). "Several drugs such as biguanides, sulphonylureas and insulin have been employed for the treatment of diabetes; however none has been able to cure the disease." (PMID 24250443, 2012). "Normally, pancreatic islet β-cells respond to increased metabolic demands by increasing their mass and insulin synthetic and secretory activity, as demonstrated both in rodent models of obesity without diabetes and in nondiabetic obese humans." (PMID 22110477, 2012). "Rapid recovery from diabetes in response to AG490 therapy, inefficiency of AG490 on the C-peptide levels, the lack of any AG490 effect on leukocyte islet infiltration- are all in agreement with improved insulin sensitivity in peripheral target tissues." (PMID 22615750, 2012). "Indeed, FXR has been demonstrated to regulate insulin secretion and sensitivity and FXR ligands reduce lipid and glucose levels in murine models of diabetes." (PMID 23106848, 2012). "Annual screening of carbohydrate status, such as hemoglobin A1c, a fasting or postprandial glucose, and insulin levels, is suitable in lean children without a family history of diabetes." (PMID 22559301, 2012). "Diabetes mellitus is a chronic disease characterized by elevated blood sugar levels resulting from either lack of insulin production or resistance to insulin." (PMID 22454632, 2012). "There are currently no studies comparing the levels of exogenous insulin in milk compared to that produced endogenously in mothers with or without diabetes mellitus." (PMID 22500167, 2012). "In addition to impaired insulin biosynthesis, understanding impaired insulin secretion and beta cell failure, including apoptosis in glucolipotoxicity-induced ER stress conditions, could have important implications for the development of therapeutic strategies for type 2 diabetes mellitus." (PMID 22474424, 2012). "However, the prevalence of diabetes mellitus may have been underestimated and the control group of osteoarthritis is not ideal, due to a not yet understood association between osteoarthritis and insulin." (PMID 23186328, 2012). "The glucose clamp-derived index of insulin sensitivity (Si index; adjusting for insulin concentration during clamp) was correspondingly lower in the diabetes group compared to the non-diabetic group." (PMID 23185996, 2012).
diabetes (continued). "Diabetes mellitus (DM) can be described as a metabolic disorder of multiple aetiology characterised by chronic hyperglycaemia with disturbances of carbohydrate, fat, and protein metabolism resulting from defects of insulin secretion, insulin action, or a combination of both." (PMID 22347666, 2012). "This suggests that the exogenous insulin used for treatment of type 1 diabetes is transported into milk with similar affinity to endogenous insulin in mothers without diabetes." (PMID 22500167, 2012). "One probable reason is that in absence of umbelliferone, decreased insulin secretion in this group, have not been reversed to the normal levels, so hyperglycemic and hyperlipidemic conditions induced by diabetes, were not improved." (PMID 25050248, 2012). "It is not uncommon for a patient who has not been diagnosed with diabetes mellitus to become hyperglycemic and require insulin therapy in the perioperative period." (PMID 23209941, 2012). "Our aim was to perform a systematic review and meta-analysis on the association between fasting glucose, fasting insulin, HOMA-IR and incident cardiovascular disease in individuals without diabetes." (PMID 23300589, 2012). "As we unfortunately did not have information about the diabetes duration and insulin requirement, as well as metabolic control and body mass index, we hope that our planned studies in this field will answer these questions." (PMID 22526616, 2012). "Unlike late-stage diabetes, fasting serum insulin concentrations were higher and GTT pattern approximated to normal in chicory-treated early-stage diabetic rats." (PMID 23352214, 2012). "The present meta-analyses showed that fasting glucose, fasting insulin and HOMA-IR were all associated with incident cardiovascular disease in individuals without diabetes." (PMID 23300589, 2012). "4% had been diagnosed with diabetes or pre-diabetes; of those, none were on insulin and 2% were on an oral hypoglycemic agent." (PMID 26097796, 2012). "Approximately 15% of all patients with diabetes will, at some time, have non-healing wounds, despite insulin treatment and a meticulously-controlled diet, and this is the leading cause of lower extremity amputation." (PMID 22662132, 2012). "The same effects are not observed in chicory-STZ group presumably because of lack of insulin in advanced diabetes." (PMID 23352214, 2012). "In support of this hypothesis, HO-1 upregulation has been shown to improve insulin sensitivity and glucose metabolism in SHR which could be another potential renoprotective mechanism in diabetes." (PMID 22518298, 2012). "For example, in a Lewis rat STZ model, increased retinal expression of IL-1B, TNFα, ICAM-1 and iNOS with diabetes has been demonstrated to be prevented by good glycemic control, but once established can not be reversed by long-term insulin therapy." (PMID 21575160, 2011). "In summary, this study supports that the 6 g/d BBG beverage consumed over 12 weeks improves insulin sensitivity among hyperglycemic individuals who have no prior diagnosis of diabetes mellitus and no change in body weight." (PMID 21846371, 2011). "Furthermore, mice with over-expression of Ffarr1 show impaired beta cell function and develop diabetes, whereas disruption of the gene reduces FFA-stimulated insulin release and, possibly protects from diabetes." (PMID 21552566, 2011). "Insulin is a safe and effective method of treating all these patients, irrespective of type of diabetes." (PMID 21232158, 2011). "These values are lower than the ones we find in humans without diabetes and very similar to those in diabetic patients under insulin treatment, respectively." (PMID 21559266, 2011). "Type 2 diabetes mellitus (T2DM) is a metabolic disorder characterized by dysregulation of carbohydrate, protein, and fat metabolism resulting from defects in insulin secretion, insulin action, or both." (PMID 20953398, 2011).
diabetes (continued). "Top loci associated with fasting insulin [ln(μIU/mL)] and HOMA-IR in African Americans without diabetes from HyperGEN." (PMID 21901158, 2011). "In individuals without diabetes, approximately 50% of daily insulin secretion is basal, while the remainder is prandial." (PMID 21517955, 2011). "Previously, we have examined whole-retina transcriptional changes in the same rat model after three months of diabetes using Illumina RatRef12 microarrays but with fewer samples per group (n = 4) and no insulin-treated diabetic group." (PMID 21575160, 2011). "Therefore, this study examined the effect of insulin therapy on IHD and CVA risks among elderly diabetics." (PMID 21978180, 2011). "Other algorithms have been tested clinically, such as fuzzy logic, which is developed from qualitative approximations of clinical judgment by diabetes practitioners, a combination of MPC and PID algorithms for insulin and glucagon delivery, or a PID with insulin feedback." (PMID 22071283, 2011). "Using a widely recognized mouse model of diabetes here we demonstrate that, at both hyper- and normoglycemic conditions, MSC transplantation induces pancreatic islet recovery that results in an improvement endogenous insulin production." (PMID 21304603, 2011). "Furthermore, sulfatide inhibits diabetes development in NOD mice, and presence of sulfatide in vitro resulted in greatly reduced proliferation of an insulin-specific T-cell clone." (PMID 21143521, 2011). "Since the discovery of insulin more than 80 years ago, the treatment of diabetes mellitus has not changed much." (PMID 21747828, 2011). "If the efficacy of insulin signaling does indeed play an important role in DRG function, it is reasonable to propose that factors common to both diabetes models could play an important role in modulating IRS2 signaling regardless of available insulin levels." (PMID 21754917, 2011). "The experimental diabetes caused by STZ also decreased the PNP-S in the rat bile, and the insulin treatments were not able to compensate this reduction." (PMID 22145108, 2011). "Recent studies have shown that Aliskiren improves insulin sensitivity in type 2 diabetic mice; however, there are no reports on Aliskiren's effect on blood glucose in type 1 diabetes mellitus." (PMID 21747829, 2011). "In one study of patients with acute myocardial infarction without diabetes, the rise in inflammation was attenuated in the group receiving insulin infusion compared with the group not receiving insulin, although glucose levels were similar in both groups." (PMID 21517955, 2011). "In the light of this, we further investigated the fundamental relationship between serum amylase and cardiometabolic aspects by reanalyzing previous data which comprised subjects without diabetes treatment with oral hypoglycemic drugs or insulin (n = 2,344)." (PMID 22004561, 2011). "Type 2, noninsulin-dependent diabetes mellitus (NIDDM), in which the body does not produce enough, or properly use, insulin, is the most common form of the disease, accounting for 90–95% of diabetes." (PMID 22134398, 2011). "It is, thus, possible that insulin treated ongoing diabetes rather than preventing incipient disease in some animals." (PMID 21647401, 2011). "On the other hand, Type 2 diabetes mellitus (T2DM), characterized by target-tissue resistance to insulin, is epidemic in industrialized societies and is strongly associated with obesity; however, the mechanism by which increased adiposity causes insulin resistance is unclear." (PMID 21686173, 2011). "One of the problems of human clinical studies of diabetes and AD has been the fact that measurements of glucose metabolism and insulin levels at the time of death in an AD patient are not reflective of the pathological mechanisms that lead to this stage." (PMID 22654727, 2011). "Diabetes mellitus was defined as fasting glucose ≥126 mg/dL, nonfasting glucose ≥200 mg/dL, or use of oral hypoglycemic medication or insulin (n = 395)." (PMID 22114591, 2011).
diabetes (continued). "Despite this, these findings suggest that LPI/GPR55 regulate insulin secretion, and that drugs that target GPR55 may be used in the treatment of diabetes." (PMID 21904624, 2011). "Interestingly, the ICs were enriched for miRNA targets with functional roles in diabetes-relevant pathways e.g. the pathways T1D, T2D, MODY, oxidative phosphorylation, insulin, cytokine-cytokine receptors and type 1 interferon." (PMID 21294859, 2011). "This increased risk is hypothesized to be secondary to several factors, such as increased circulating insulin and insulin-like growth factor (IGF-1), and to effects of treatment for diabetes." (PMID 21672406, 2011). "Top copy variable loci associated with fasting insulin [ln(μIU/mL)] and HOMA-IR in African Americans without diabetes from HyperGEN." (PMID 21901158, 2011). "It is not surprising that after one month of insulin treatment blood glucose levels of the diabetic rats were not lowered/corrected, since insulin directly treats diabetes on a daily basis—as a short-term and not a long-term treatment." (PMID 21747829, 2011). "One patient requires daily steroids, treatment is not reported in one, the surgical patient requires digestive enzymes, and one patient requires NPH insulin for diabetes but did not have recurrence of disease." (PMID 21205323, 2011). "This was accomplished by inducing severe diabetes without insulin treatment, and it provided an advantage when interpreting the data, because any changes were directly related to the effects of exercise without a reduction in blood glucose." (PMID 21912535, 2011). "The newly diagnosed group was not different from the non-diabetes group in terms of hemoglobin levels, anemia, BMI, smoking, physical activity, cholesterol and insulin levels." (PMID 21464957, 2011). "Daily subconjunctival administration of 20 mIU of insulin for 4 consecutive days to rats with 4 weeks of STZ-induced diabetes did not reduce the hyperglycemia." (PMID 22046295, 2011). "Among people with diabetes, 20% of men and 30% of women reported the use of insulin (data not shown)." (PMID 22005625, 2011). "The goal of this study was to identify molecular changes in the rodent retina induced by diabetes that are not normalized by insulin replacement and restoration of euglycemia." (PMID 21575160, 2011). "Where subjects with diabetes are to be studied, the HEC or insulin-modified FSIVGTT should be used." (PMID 22112229, 2011). "Subcutaneous insulin remains the backbone for the treatment of diabetes mellitus in Europe when oral antidiabetic medicinal products are not effective or no longer sufficient." (PMID 21736748, 2011). "In this study we identified a number of gene expression changes evident at 1 month of diabetes that were not reversed by chronic insulin therapy." (PMID 21575160, 2011). "All ‘pre–T1D’ samples were obtained when these individuals had diabetes-associated autoantibodies (GAD65, IA2 and Islet Cell Antibodies), but with normal blood glucose levels and without insulin treatment." (PMID 21980303, 2011). "In patients with hypertriglyceridemia without hypertension and diabetes, myocardial glucose metabolism was not significantly reduced under insulin clamping, but skeletal muscle and whole-body glucose metabolism was significantly reduced." (PMID 21841971, 2011). "The retina transcriptome (22,523 genes and transcript variants) was examined after three months of streptozotocin-induced diabetes in male Sprague Dawley rats with and without insulin replacement for the later one and a half months of diabetes." (PMID 21575160, 2011). "The goal of the current study was to identify molecular alterations induced in the retina with diabetes that are not normalized by chronic insulin treatment, using a well-characterized rodent model of insulin-dependent diabetes." (PMID 21575160, 2011). "One study reported that TCR from humans with diabetes and non-obese mice with diabetes mimic insulin and the insulin receptor." (PMID 21901158, 2011).
diabetes (continued). "We previously reported that in older βTSC2−/− mice, constitutive hyperactivity of mTORC1 induces a negative feedback mechanism and attenuation of insulin signalling that results in decreased pancreatic beta cell mass and development of diabetes mellitus." (PMID 21886784, 2011). "Once the remission phase is over, HbA1c levels are more likely to reflect actual diabetes management, rather than endogenous insulin secretion." (PMID 21966469, 2011). "In both the OF and OP groups, the duration of diabetes was not different for insulin users compared to non-users." (PMID 21978180, 2011). "Diabetes mellitus is diagnosed by abnormal glucose tolerance tests (OGTT), alternatively a direct quantification of hypoinsulinemia can be performed by measurements of serum levels of insulin or c-peptide." (PMID 22133269, 2011). "Diabetes is a rapidly growing health problem worldwide and chronic disease wherein the pancreas does not produce enough insulin (type 1 diabetes), or the body does not respond correctly to insulin and relative insulin deficiency (type 2 diabetes)." (PMID 22187651, 2011). "Diabetes is a chronic disease that occurs when the pancreas does not produce enough insulin, and/or when the body cannot effectively use the insulin it produces." (PMID 21584245, 2011). "Several other inflammatory response genes induced with diabetes were also not rescued by insulin treatment." (PMID 21575160, 2011). "The use of a Type I diabetes animal model allows for the examination of retinal gene expression with and without insulin treatment and at different durations of diabetes in a manner not possible in humans." (PMID 21575160, 2011). "Diabetes is characterized as hyperglycemia that occurs when the pancreas does not produce enough insulin, or when the body cannot effectively use the insulin it produces." (PMID 20550665, 2010). "Among diabetic patients, 10%–20% fall into the category of insulin-dependent diabetes mellitus (IDDM) or type 1 diabetes, which generally appears before age 40, frequently in adolescence, and results from autoimmune destruction of insulin producing pancreatic β-cells." (PMID 20700401, 2010). "Compared with individuals without diabetes by glucose criterion, those with newly diagnosed diabetes were older and more obese, hypertensive, dyslipidemia, and insulin resistant in men and in women." (PMID 21076541, 2010). "In summary, we have integrated gene expression and targeted metabolomic data to present a comprehensive overview of RSG-induced changes in a diabetes mouse model and improved the molecular understanding of how RSG ameliorates diabetes through its effect on the major insulin-sensitive tissues." (PMID 20953342, 2010). "In conclusion, chronic hyperinsulinemia, either with or without clinically manifest type 2 diabetes mellitus, is a possible factor favoring cancer progression due to the mitogenic effect of insulin." (PMID 24281091, 2010). "Our study did not aim to explain the progression of BC during insulin treatment, but several studies investigating the role of insulin on protein metabolism in diabetes mellitus have provided useful data." (PMID 20721344, 2010). "The development of continuous subcutaneous insulin infusion (CSII) pumps and short-acting insulin analogues exhibiting beneficial pharmacokinetic properties represents important advances in the treatment of diabetes and will be reviewed herein." (PMID 20589066, 2010). "• However, ICU and hospital mortality rates were similar in patients with and without a history of insulin-treated diabetes." (PMID 20132545, 2010). "Fasting plasma insulin levels were significantly higher in both groups of obese with and without diabetes compared to NW." (PMID 20426869, 2010). "The restraints of using insulin infusion in patients in the ICU include a lack of inpatient diabetes management education for the hospital staff in addition to the absence of a treatment algorithm suited for the real-life hospital setting in Brazil." (PMID 20663179, 2010).